INS (insulin)
Diseases named in the same sentence as INS in open-access papers (continued):
Sharing a sentence is not in itself a finding about the gene and the disease.
diabetes (continued). "We report a case of a woman who was diagnosed with diabetes mellitus at the age of 26, was on oral hypoglycemic agents (OHA), and was shifted to insulin therapy as she became non-responsive to OHA in a short span of six years, which was alarming." (PMID 38249240, 2023). "The historic label for monogenic diabetes was ‘Maturity-Onset Diabetes of the Young’ (MODY), with the classic triad of diabetes diagnosed under 25 years of age, with autosomal dominant family history of diabetes, and without insulin requirements." (PMID 37234800, 2023). "Another online survey of 3455 patients with diabetes found that TIR was the primary indicator of most concern in patients with type 1 diabetes and type 2 diabetes with or without insulin therapy." (PMID 36514151, 2022). "Type 1 diabetes mellitus (T1DM) is an autoimmune disease, due to a large number of islet β cells damaged, resulting in an absolute lack of insulin, ultimately relying on insulin therapy." (PMID 36090587, 2022). "In addition, MTs overexpression exerts a positive effect on alleviating diabetes and diabetic cardiovascular complications through attenuating oxidative stress, whereas another study indicated a negative correlation between MT-1 overexpression and insulin secretion." (PMID 36291566, 2022). "One hundred sixty-seven people of the participants treated for diabetes (63.74%), had poorly controlled diabetes, and 83 people of ones with diabetes (with high FBS or treated with drugs or insulin (21.50%)), did not know they had it." (PMID 35619088, 2022). "The potential use of other diabetes technologies such as continuous subcutaneous insulin infusion systems or hybrid-closed loop systems is options that have not been explored in patients with DM-ICIs but could have added benefits in certain patient subgroups." (PMID 36387939, 2022). "Individuals with type 2 diabetes tended to be older and they had higher BMI, FBG, PBG, F-insulin, P-insulin, HOMA-IR, TG, dietary energy intake, dietary lipid intake, and serum XO activity but lower HDL-C than individuals without diabetes." (PMID 35425797, 2022). "Diabetes mellitus (DM) is a group of metabolic disorders in which blood sugar levels are high over a prolonged period and is due to either the pancreas not producing enough insulin or the cells of the body not responding properly to the insulin produced." (PMID 35300755, 2022). "The role of the VEPH1 gene in the development of diabetes has not yet been studied, but Melted, an ortholog of VEPH1 in Drosophila, is known to be involved in insulin/PI3K signaling." (PMID 35885959, 2022). "Diabetes‐related biomarkers including haemoglobin‐A1c (HgbA1c) and CRP were included in eight of 20 non‐insulin trials and none of the insulin trials." (PMID 35128745, 2022). "Current data suggest a prevalence of DKA ranging from approximately 50 to 100 events per 1000 adult patients with Type 1 diabetes mellitus (DM), with a higher prevalence in women, non-whites, and the patient being treated with insulin injections (as opposed to infusion pumps)." (PMID 35186583, 2022). "In individuals without diabetes, inflammation reflected by increased CRP levels and insulin levels precedes glucose intolerance." (PMID 35757631, 2022). "Contrary to the proband, diabetes in the father was polygenic-like type 2 diabetes, as it was diagnosed in adulthood and was treated with metformin and DPP4 inhibitor without any insulin." (PMID 35227307, 2022). "Second, as we did not measure insulin values in this study, the ratio of insulin-to-fasting glucose across NGT, prediabetes, and diabetes, was not available to correlate insulin levels to triglycerides." (PMID 35331213, 2022). "This study aimed to assess the differences in requirement for insulin treatment and HOMA2 and/or HbA1c in patients with or without diabetes autoantibodies." (PMID 34533636, 2022).
diabetes (continued). "Providers had low confidence in identifying which patients with insulin-requiring diabetes would benefit from insulin pump therapy, and this did not improve with Project ECHO Diabetes." (PMID 36589850, 2022). "In diabetes, the pathogenetic role and mechanisms of insulin is highly complex, and a large volume of literature now strongly favor the view that β cell dysfunction but not insulin resistance may be the central defect responsible for the development of Type 2 diabetes." (PMID 36482911, 2022). "Secondly, patients with type 1 diabetes (T1DM) who depend on insulin from the onset of the disease were less likely to have been included in the study; this is because insulin, despite its near-exclusive indication for DM, was not considered when identifying diabetic patients." (PMID 36011478, 2022). "In this case study, a 38-year-old man with type 2 diabetes mellitus (T2DM) was admitted due to complaints of excruciating abdominal pain, vomiting, and non-adherent to his insulin medication." (PMID 36110486, 2022). "In summary, our study showed that insulin therapy does not alter visual outcomes for T2 diabetics receiving anti-VEGF injections and patients do not need to alter their diabetes medication to optimize their eye care." (PMID 35227220, 2022). "Baseline beta‐cell function (HOMA2‐%B) and insulin sensitivity (HOMA2‐%S, the reciprocal of HOMA2‐IR) exhibited hyperbolic relationship in participants without diabetes but not in those with diabetes." (PMID 35174618, 2022). "Patients with diabetes who had previously received sharps disposal instruction were 4.143 times (AOR = 4.143, 95% CI = 1.642–10.450) more likely to dispose of insulin needles safely than those who had not." (PMID 36568796, 2022). "In univariable analysis, age, preoperative BMI, duration of T2DM, no insulin use, FBS, HbA1c, and no family history of obesity were the best preoperative predictors of diabetes remission 1-year and 3 years after surgery." (PMID 36289529, 2022). "Earlier this was also called Non-insulin Dependent Diabetes Mellitus (NIDDM), but this term is no longer used because insulin is often used in the management of NIDDM." (PMID 35203540, 2022). "Patients with stress hyperglycemia have higher plasma insulin levels and evidence of reduced insulin sensitivity, as suggested by higher HOMA and TyG index, that is independent of preexisting diabetes." (PMID 36059840, 2022). "Although we did not try to classify subjects according to diabetes type, the majority of participants that use “Insulin only” as glucose lowering treatment most likely have type 1 diabetes, even if some older people with type 2 diabetes might also use “Insulin only” (ex." (PMID 35701772, 2022). "Insulin-resistant adults without diabetes displayed higher levels of circulating 3-DG, AGEs, and lower concentrations of soluble RAGE (sRAGE) compared with their insulin-sensitive (IS) peers." (PMID 36432614, 2022). "The results revealed that as diabetes progressed, a significant negative correlation was observed between changes in the CD34-positive localization region and INS-positive localization region in the islet structure (r = −0.9092, p < 0.0001)." (PMID 36467676, 2022). "Approximately 90% of diabetes cases can be considered T2DM, which occurs when cells do not respond appropriately to circulating insulin (called insulin resistance) and thus need higher insulin levels to regulate sugar processing." (PMID 35324794, 2022). "In this clinical study, we found that empagliflozin decreased insulin, increased glucagon, and increased NEFAs and BHB blood levels in individuals without diabetes." (PMID 36359767, 2022). "Treatment of non-obese diabetic (NOD) mice with DAC prevented diabetes development by cyclophosphamide, while application of DAC to HFD fed ob/ob mice improved insulin sensitivity." (PMID 36246880, 2022).
diabetes (continued). "Type 1 diabetes mellitus (T1DM) was excluded because of negative diabetes autoantibodies, including glutamate decarboxylase antibody (GADA), protein tyrosine phosphatase antibody (IA-2A), insulin antibody (IAA) and islet cell antibody (ICA)." (PMID 35346144, 2022). "Type 2 diabetes mellitus (T2DM) is a complex metabolic disorder that is characterized by hyperglycemia, insulin resistance, and lack of insulin production." (PMID 36079819, 2022). "Clues to make a LADA diagnosis are suggested in patients with diabetes when he/she is (a) positive for GADA, IA2, ZnT8A, (b) older than 30 or 35 years of age, and (c) not insulin-dependent for at least 6-12 months." (PMID 35846301, 2022). "Scientists trying to explain the frequent occurrence of exocrine pancreatic insufficiency in diabetes have put forward hypotheses about the dysregulation of exocrine secretion due to diabetic neuropathy and atrophy of exocrine tissue due to the lack of local trophic action of insulin." (PMID 35431983, 2022). "Diabetes induction in group II elevated both of FBG (244.3 mg/dl) and FTA levels (299.4 μmol/mL) and decreased serum insulin level (5.2 μU/mL) when compared to negative control group I." (PMID 36544223, 2022). "The majority of the participants had one pregnancy with GDM (73.6%), did not use insulin as GDM treatment (83.0%), had no family history of diabetes (67.9%), currently were not breastfeeding (63.2%), and had no history of postpartum depression (94.3%)." (PMID 36141683, 2022). "Current studies have shown that patients with pre-diabetes or type 2 diabetes mellitus often have defects in the effect of incretin, while exogenous GIP does not show a good insulin-promoting effect." (PMID 36583004, 2022). "Therefore, among those with diabetes, whether T1D or T2D, using insulin may homogenize dietary behaviors compared to those with T2D but not taking insulin, and both groups may vary from the group of adults who do not have diabetes." (PMID 36014790, 2022). "Type 2 diabetes mellitus (T2DM), on the other hand is not insulin dependent; rather it is characterized by insulin resistance due to the inability of cells to respond to insulin followed by compensatory hyperinsulinemia." (PMID 34225729, 2021). "A thorough understanding of whether diabetes influences cancer prognosis, high-quality databases and a prospective population-based studies are needed to compare and analyse the occurrence of specific cancers between subjects with or without diabetes and with the variations of insulin levels also." (PMID 34535145, 2021). "As in the Diabetes Prevention Trial–Type 1 (DPT-1), TrialNet and Pre-POInT trials, we observed no signs of allergy or intolerance to orally administered insulin." (PMID 33515070, 2021). "It has been found that MDCS-CC participants suffering from diabetes have an increased risk of IMT progression at the bifurcation (IMTbif) but not on the common carotid artery (IMTcca), however, it was also found that insulin resistance alone could not explain the development of atherosclerosis." (PMID 34063058, 2021). "The severity of STZ + N-induced diabetes is much lower than that of diabetes induced by STZ alone; rats manifest moderate hyperglycemia and do not require exogenous insulin to survive." (PMID 34182970, 2021). "Our estimated partial Spearman’s correlations show that creatinine and hs-CRP, as well as fasting glucose and insulin, were inversely correlated with 25(OH)D and positively correlated with PTH among individuals without diabetes." (PMID 34531372, 2021). "According to a meta-analysis that studied the relationship between insulin and CVD mortality in people without diabetes, those with the highest degree of IR compared to the lowest had a higher risk of CVD mortality." (PMID 34684300, 2021). "The role of protein and fat as macronutrients in children with diabetes has been recognized, yet CHC (not taking fat and protein into account) is still the dominant form of calculating insulin boli." (PMID 34684559, 2021).
diabetes (continued). "INPP5F can be used as a negative feedback regulator of insulin signal and downregulation of INPP5F in diabetes mellitus has cardioprotective effect." (PMID 33407475, 2021). "Subjects were classified into the following 5 categories based on diabetes status: no diabetes, impaired fasting glucose (IFG), new onset diabetes, diabetes treated with oral hypoglycemic medication, and diabetes treated with insulin." (PMID 34521935, 2021). "In the absence of an established diagnosis of diabetes, calculation of the homeostatic model assessment (HOMA; fasting insulin × fasting glucose/405) is required as part of the NFS for assessment of insulin resistance." (PMID 36090909, 2021). "There are several studies linking ART and HIV to metabolic syndrome and diabetes, but there are no prior studies assessing the effect of LNS supplementation on glucose metabolism and insulin function among people with HIV." (PMID 34657634, 2021). "Diabetes mellitus (DM) is a chronic metabolic disorder characterized by impaired glucose tolerance and disturbance of carbohydrate, protein, and fat metabolism, resulting from a lack of insulin or dysregulated insulin signaling." (PMID 34603896, 2021). "Globally, diabetes mellitus (DM) is the most common non-communicable metabolic disease in which the person has a high blood glucose (blood sugar) level, either due to inadequate insulin production or because the body’s cells do not respond properly to insulin or both." (PMID 34360135, 2021). "The mother was considered non-diabetic,but had delayed insulin secretion via OGTT and islet function test, which is one of the characteristics of diabetes." (PMID 33604390, 2021). "As previously indicated, IGFBP2 is reported to protect against diabetes and obesity onset and here a negative correlation between circulating IGFBP2 and insulin, glycemia, leptin and body weight was found in males." (PMID 34975768, 2021). "Among the types of diabetes, type 2 diabetes mellitus (T2DM) represents 90% of cases, and it occurs when the body does not properly use the insulin produced or does not produce the required hormone capable of controlling blood glucose." (PMID 34366888, 2021). "The percentage of women with gestational diabetes mellitus GDM was 16%, including 2.3% for cases treated with insulin (GDM-2) and 13.7% for cases treated with dieting only (GDM-1), but this cohort had no chronic diseases (no preexisting diabetes mellitus)." (PMID 33671089, 2021). "We suggest parameters for future prospective trials with a target blood glucose range of 90–140 mg/dL to guide insulin therapy and that insulin initiation should be guided by the MHG, rather than admission glucose or a patient history of diabetes." (PMID 33420311, 2021). "Higher triglyceride was independently associated with higher plasma glucose, higher HbA1c, higher serum insulin, and higher HOMA for insulin resistance in the whole cohort and sub-cohorts of participants with or without diabetes." (PMID 34930280, 2021). "Type 2 diabetes mellitus (T2DM), called non-insulin dependent diabetes, is a chronic disease that occurs when the body cannot effectively use the insulin it produces." (PMID 34679681, 2021). "The HR for CVD events was 1.06 (95% CI 1.02–1.11) and 1.42 (95% CI 1.35–1.49) among patients with diabetes and CKD not taking insulin and taking insulin, respectively, each versus those with prior CVD." (PMID 33648518, 2021). "Then, in subjects with diabetes, a lack of GIP amplification of the late phase insulin response to glucose was observed." (PMID 35054422, 2021). "The GlyG was significantly higher in patients without diabetes in the ICU compared to patients without diabetes in the wards, while HOMA2%B based on glucose and insulin was significantly higher in the ICU patients compared to patients in the wards." (PMID 33466617, 2021).
diabetes (continued). "Diabetes mellitus (DM) is a heterogeneous disease, out of which type 1 DM (T1DM) is characterized by absolute lack of insulin that mainly results from autoimmune destruction of pancreatic beta cell mass (type 1A)." (PMID 33803255, 2021). "The reduction of PPI in healthy volunteers is probably the result of the rapid adaptation of insulin secretion to reduced PPG responses, which is not optimal in diabetes patients." (PMID 33658478, 2021). "Type 1 diabetes mellitus (T1DM) patients occasionally develop disordered eating behaviors, leading to insulin manipulation without medical consultation, targeting to achieve weight control." (PMID 34371885, 2021). "In the absence of insulin production, BHB synthesis would continue unabated, as seen in type 1 diabetes mellitus (T1DM)." (PMID 34356863, 2021). "After a course of administration of Galega officinalis extract at a dose of 600 mg/kg body weight, the concentration of insulin and C-peptide did not change in animals of the control group, while in animals with DM increased (1.7 and 2.2 times, respectively) relative to diabetes level." (PMID 34572994, 2021). "Acute hyperglycemia in patients without diabetes increases the procoagulant activity of Factor VII and increases thrombin–antithrombin complexes and soluble tissue factor (sTF) in an insulin‐independent manner." (PMID 33463901, 2021). "Age, diabetes, severity of injury (APACHE II and SOFA scores), length of stay, GC outcomes, measurement frequency, and insulin administration were all not significantly different." (PMID 33475909, 2021). "By contrast, 6 weeks of metformin treatment reduced body weight, improved insulin secretion, lowered LDL and triglyceride levels in an elderly population exhibiting impaired glucose tolerance but no previous history of diabetes." (PMID 34660673, 2021). "Diabetes diaries are part of DSME for both patients with and without insulin treatment, both type I and type II." (PMID 33740024, 2021). "One study conducted among obese individuals without diabetes reported that prolonged (6 months) TNF inhibition significantly decreased fasting glucose and increased adiponectin, probably reflecting improved insulin sensitivity." (PMID 34616762, 2021). "Intraperitoneal injection of resveratrol lowered plasma glucose and increased insulin in normoglycemic Wistar rats; however, no glucose-lowering effect was observed in STZ-induced diabetes." (PMID 35098034, 2021). "Although the association between C-peptide levels and CVD was independent of baseline insulin or sulphonylureas use, we cannot dismiss the possibility that C-peptide levels may reflect more subtle variations in treatment regimen, individual anti-diabetes medications, and/or their dosage." (PMID 34879878, 2021). "Type 2 diabetes mellitus (T2DM) is the most common form of diabetes, accounting for 90%–95% of all diabetic patients, which is primarily due to the relative lack of insulin secretion or reduced sensitivity to insulin." (PMID 32467722, 2020). "In the United Kingdom Prospective Diabetes Study (UKPDS), hyperinsulinemia and insulin resistance were not mitigated by insulin treatment, and fasting plasma insulin levels even rose." (PMID 32819363, 2020). "Furthermore, a reduction in the diabetes-induced increases in MDA and conjugated diene levels, markers of oxidative stress, were associated with an improvement in cardiac function without affecting the plasma glucose or insulin levels upon treatment with vitamin E." (PMID 32244448, 2020). "Hence, in face of resistance to insulin in the glycemic context, insulin-driven Erk/RSK may transduce a variety of mTORC1-mediated disease aspects of T2D (e.g., beta cell failure, obesity, NAFLD, dyslipidemia, hypertension, diabetes macro- and micro-vascular disease)." (PMID 32128655, 2020). "Insulin use and blood glucose management strategies vary greatly among centers performing CABG in both patients with and without diabetes." (PMID 33118731, 2020).